RNF135 (ring finger protein 135)
Description:
E2-dependent E3 ubiquitin-protein ligase that functions as a RIGI coreceptor in the sensing of viral RNAs in cell cytoplasm and the activation of the antiviral innate immune response. Together with the UBE2D3, UBE2N and UB2V1 E2 ligases, catalyzes the 'Lys-63'-linked polyubiquitination of RIGI oligomerized on viral RNAs, an essential step in the activation of the RIG-I signaling pathway. Through a ubiquitin-independent parallel mechanism, which consists in bridging RIGI filaments forming on longer viral RNAs, further activates the RIG-I signaling pathway. This second mechanism that synergizes with the ubiquitin-dependent one would thereby allow an RNA length-dependent regulation of the RIG-I signaling pathway (Probable). Associated with the E2 ligase UBE2N, also constitutively synthesizes unanchored 'Lys-63'-linked polyubiquitin chains that may also activate the RIG-I signaling pathway.
Synonyms: REUL; Riplet; L13; MGC13061; MMFD
Tractability: Small molecule: a structure with a bound ligand is known. PROTAC: ubiquitination databases record sites on it.
Gene: Protein-coding gene on chromosome 17 (30,970,984 to 30,999,911, forward strand). Ensembl gene ENSG00000181481.
Subcellular location: Cytoplasm; Cytoplasm, Stress granule
Subcellular location (Human Protein Atlas): Vesicles
Pathways (Reactome):
Immune System: DDX58/IFIH1-mediated induction of interferon-alpha/beta; NF-kB activation through FADD/RIP-1 pathway mediated by caspase-8 and -10; Negative regulators of DDX58/IFIH1 signaling; TRAF3-dependent IRF activation pathway; TRAF6 mediated IRF7 activation; TRAF6 mediated NF-kB activation
Disease: SARS-CoV-2 activates/modulates innate and adaptive immune responses
Metabolism of proteins: Ovarian tumor domain proteases
Gene Ontology:
Molecular function: identical protein binding; protein binding; ribonucleoprotein complex binding; RIG-I binding; ubiquitin protein ligase activity; ubiquitin-protein transferase activity
Biological process: antiviral innate immune response; free ubiquitin chain polymerization; positive regulation of interferon-beta production; protein homooligomerization; protein K63-linked ubiquitination; protein polyubiquitination; protein ubiquitination; regulation of innate immune response; RIG-I signaling pathway; innate immune response
Cellular component: cytoplasm; cytoplasmic stress granule; ribonucleoprotein complex; cytosol
Genetic constraint (gnomAD): Loss-of-function variants: 46 observed, 39.44 expected, observed/expected ratio (o/e) 1.17, 90% interval 0.92 to 1.49. The upper end of that interval is the gene's LOEUF score, 1.49, which puts it in group 6 of 6, group 1 being the genes least tolerant of losing a copy. Missense variants: 539 observed, 526.58 expected, observed/expected ratio (o/e) 1.02, 90% interval 0.95 to 1.1. Synonymous variants: 238 observed, 217.43 expected, observed/expected ratio (o/e) 1.09, 90% interval 0.98 to 1.22.
Homologues: Orthologues: chimpanzee RNF135 (98% identical), macaque RNF135 (91% identical), dog RNF135 (66% identical), pig RNF135 (60% identical), guinea pig RNF135 (55% identical). Paralogues in human: RFPL4A (15% identical), RFPL4AL1 (15% identical), RFPL4B (14% identical), RFPL1 (13% identical), RFPL3 (13% identical), RFPL2 (12% identical), SPRYD4 (10% identical), CD86 (7% identical), CD274 (6% identical), CD80 (6% identical), RNF152 (6% identical), PDCD1LG2 (4% identical).
Diseases named in the same sentence as RNF135 in open-access papers:
RNF135 is named in the same sentence as 46 diseases in open-access papers, as found by Europe PMC text mining. Sharing a sentence is not in itself a finding about the gene and the disease. The quoted sentences say what the papers report.
glioblastoma (10 papers, 2016 to 2025). The most malignant astrocytic tumor (WHO grade IV). "Taken together, our findings demonstrate the biological effects of RNF135 in glioblastoma cell proliferation, migration and cell cycle, and its role in the progression of glioblastoma may be associated with the ERK signal transduction pathway." (PMID 26856755, 2016). "Earlier research established that RNF135 influences the growth of human glioblastoma through the ERK pathway." (PMID 36495591, 2022). "Several studies have investigated RNF135 in cancer, including tongue cancer, glioblastoma and Hepatocellular Carcinoma." (PMID 36495591, 2022). "Targeting RNF135 and downregulating miR-485-3p enhanced glioblastoma cell proliferation and migration." (PMID 36495591, 2022). "The data of quantitative real-time PCR showed that glioblastoma tissues presented much higher transcription levels of RNF135 than NB tissues (P < 0.05)." (PMID 26856755, 2016). "We examined the degree of co-expression of RNF135 and P-Erk in glioblastoma samples and NB tissues with fluorescent double-labelling." (PMID 26856755, 2016). "In our study, we confirmed that RNF135 was up-regulated in glioblastoma tissues compared with normal brain (NB) tissues, and that RNF135 knockdown inhibited proliferation and migration and led to cell cycle arrest in the G0/G1 phase in vivo." (PMID 26856755, 2016). "Next, to examine the effect of RNF135 on glioblastoma cell migration, we performed wound healing and Boyden chamber assays." (PMID 26856755, 2016). "Our findings provide new insights into the role of RNF135 in the development of glioblastoma, and implicate the potential application of RNF135 in glioblastoma therapy." (PMID 26856755, 2016). "First, we confirmed that the RNF135 mRNA was highly expressed in 28 glioblastoma samples compared with 12 normal brain tissues using quantitative real-time PCR." (PMID 26856755, 2016). "In addition, various studies have shown that RNF135 plays a significant role in the proliferation and dissemination of multiple cancers such as tongue cancer, glioblastoma (GBM), hepatocellular carcinoma, and breast cancer." (PMID 39118262, 2024). "Regardless, the role of RNF135 in neurodevelopment remains unclear, though there is evidence showing that RNF135 can promote the proliferation of human glioblastoma cells in vivo and in vitro." (PMID 37108679, 2023). "Many studies have looked at how RNF135 affects the growth and migration of human glioblastoma." (PMID 36495591, 2022). "Reduced expression of RNF135 by elemene inhibits human glioblastoma proliferation and migration." (PMID 36495591, 2022). "Furthermore, we found that RNF135 and P-Erk were highly co-expressed in glioblastoma tissues compared with normal brain tissues." (PMID 26856755, 2016). "In the present study, we first investigated the RNF135 effect in glioblastoma." (PMID 26856755, 2016). "Similarly, the RNF135 protein levels in glioblastoma tissues were also higher than those in NB tissues (P < 0.05)." (PMID 26856755, 2016). "In summary, RNF135 may have significant value as a progression indicator for patients who have glioblastoma." (PMID 26856755, 2016). "In addition, using the immunofluorescence double labelling method, we found that RNF135 and P-Erk were co-localized in the cytoplasm and were highly expressed in glioblastoma samples compared with NB tissues." (PMID 26856755, 2016). "Studies have suggested that RNF135 may exhibit oncogenic functions in glioblastoma." (PMID 36702236, 2023). "This work indicated that RNF135 could modulate the Erk pathway in glioblastoma." (PMID 26856755, 2016). "However, the function and expression levels of the RNF135 gene in human glioblastoma remain unknown." (PMID 26856755, 2016). "Recent studies have demonstrated that RNF135 and RNF138 amplification activate the ERK signaling pathway in glioblastoma, which promotes cellular proliferation, migration, and invasion." (PMID 34081837, 2021).
glioblastoma (continued). "Consistent with previous studies, BIRC3 and RNF135 were all previously reported as oncogenes in glioma, while we first revealed that RNF185 may play a tumor suppressor role in glioblastoma." (PMID 35183197, 2022). "To investigate the biological implication of RNF135 cells in glioblastoma, we conducted MTT, wound healing and Boyden chamber analysis experiments to determine the effect of decreased RNF135 expression on glioblastoma cell growth and migration in vitro." (PMID 26856755, 2016). "Ring finger protein 135 (RNF135), located on chromosome 17q11.2, is a RING finger domain-containing E3 ubiquitin ligase that was identified as a bio-marker and therapy target of glioblastoma." (PMID 26856755, 2016).
viral infection (7 papers, 2009 to 2024). "During viral infection, RNF135 activate RIG-I receptor signaling to promote the release of interferon-β." (PMID 35145901, 2021). "Six genes were closely associated with viral infection, namely, LY6E, receptor-type tyrosine-protein phosphatase S (PTPRS), neurogenic locus notch homolog protein 3 (NOTCH3), tripartite motif containing 56 (TRIM56), ring finger protein 135 (RNF135), and growth arrest-specific 6 (GAS6)." (PMID 38169284, 2024).
autism (5 papers, 2016 to 2024). Persistent deficits in social interaction and communication and interaction as well as a markedly restricted repertoire of activity and interest as well as repetitive patterns of behavior. "The RNF135 gene encodes an E3 ubiquitin ligase, a pathway previously implicated in autism and intellectual disability." (PMID 38448973, 2024). "RNF135 encodes an E3 ubiquitin ligase; otherubiquitin ligase genes have already been implicated in the development ofintellectual disability and autism." (PMID 28213670, 2017). "A significantly increased frequency of genotypes carrying therare allele of the RNF135 missense variantrs111902263 (p.R115 K) has been observed in patients with autism as comparedwith healthy controls (P = 0.0019, oddsratio: 4.23, 95% confidence interval: 1.87–9.57)." (PMID 28213670, 2017). "RNF135, or Ring Finger Protein 135 or RING-Type E3 Ubiquitin Transferase RNF135 gene, is an autism candidate gene in the SFARI database involved in protein–protein and protein–DNA interactions." (PMID 37108679, 2023).
glioma (4 papers, 2008 to 2022). A benign or malignant brain and spinal cord tumor that arises from glial cells (astrocytes, oligodendrocytes, ependymal cells). "Low levels of RNF135 expression in glioma tissues correlated significantly with a better survival than those with high-expression (P = 0.000, log-rank test)." (PMID 26856755, 2016). "The IHC assay demonstrated that the RNF135 protein was highly expressed in approximately 66.9% of glioma tissues but only highly expressed in 25% of NB tissues (P = 0.009)." (PMID 26856755, 2016). "BIRC3, KLHL10 and RNF135 showed unfavorable biomarker performance in glioma samples, and only RNF185 may serve as a favorable marker." (PMID 35183197, 2022). "There was no remarkable association between RNF135 expression and the patients’ age and gender in the randomly selected glioma cases." (PMID 26856755, 2016). "Next, we conducted a series of experiments and found that knocking down RNF135 with shRNA could significantly inhibit U87 and U251 glioma cell line proliferation and migration in vitro compared with that in the PLV-Ctrl groups." (PMID 26856755, 2016). "Additionally, the IHC staining assay revealed that RNF135 was highly expressed in 66.9% of glioma patients and up-expressed in 25% of normal tissues." (PMID 26856755, 2016). "Evidence has confirmed that attenuated RNF135 expression could lead to suppressed cell growth and migration via inactivation of the Erk pathway in U87 and U251 glioma cells." (PMID 26856755, 2016). "In addition, to confirm whether the RNF135 expression levels and some other clinical factors were the independent factors of prognostic prediction in glioma patients, we performed univariate and multivariate analyses using the Cox proportional hazard regression model." (PMID 26856755, 2016). "Nevertheless, the levels of RNF135 expression were correlated with the grade of pathology classification (WHO I–II vs WHO III–IV) and histologic type in glioma patients (P = 0.000)." (PMID 26856755, 2016). "Of the 3 genes (BIRC3, RNF135 and RNF185) with both differential expression and prognostic significance, BIRC3 and RNF135 were all previously reported as oncogenes in glioma." (PMID 35183197, 2022).
tongue cancer (4 papers, 2016 to 2024). A malignant neoplasm affecting the tongue. "Our results demonstrated that RNF135 had the potential to affect the development of the tongue cancer in vitro." (PMID 27709798, 2016). "Firstly, we determined the effect of RNF135 on tongue cancer cell's proliferation." (PMID 27709798, 2016). "Overexpression of RNF135 inhibited the in vitro proliferation and invasiveness of SCC25 cells, a model of tongue carcinoma, suggesting a putative role in cancer regulation." (PMID 38448973, 2024).
hepatocellular carcinoma (3 papers, 2021 to 2024). A malignant tumor that arises from hepatocytes. "In addition, RNF135 is downregulated in human hepatocellular carcinoma (HCC) and its expression is positively associated with tumor infiltration of immune cells and patient survival." (PMID 39118262, 2024). "Moreover, we found downregulation of RNF135 in hepatocellular carcinoma, downregulation of OSMR in colorectal liver metastases and upregulation of HOXC4 in cholangiocarcinoma compared to primary liver cancers and metastatic cancers." (PMID 39766812, 2024). "RING finger protein 135 has an important role in the occurrence of many cancers; however its regulation and function of RNF135 in hepatocellular carcinoma remains unknown." (PMID 35145901, 2021).
neurofibroma (3 papers, 2021 to 2024). An intraneural or extraneural neoplasm arising from nerve tissues and neural sheaths. "In addition to GBM, RNF135 has been linked to increased risk of malignant peripheral nerve sheath tumors (MPNSTs) in neurofibroma patients with NF1 microdeletion." (PMID 39118262, 2024). "These rearrangements lead to a more severe “contiguous gene syndrome” with higher incidence of neurofibromas and MPNSTs, likely attributable to the involvement of tumor suppressor genes in co-deleted regions (e.g., SUZ12—OMIM *606245, RNF135—OMIM *611358, and ADAP2—OMIM *608635)." (PMID 33919865, 2021).
overgrowth syndrome (3 papers, 2016 to 2021). A group of syndromes caused by genetic birth defects that may lead to the development of malignancies. "RNF135 loss-of-function mutations, as well as an NF1-REPa to NF1-REPb deletion including this gene, have been implicated in an overgrowth syndrome which includes tall stature, macrocephaly, dysmorphic features, and variable additional features, including learning disability." (PMID 31652930, 2019). "In addition, both loss-of-function mutations of ring finger protein 135 (RNF135) and microdeletion of NF1-REPa to REPb including RNF135 contribute to an overgrowth syndrome including tall stature, macrocephaly, dysmorphic features, and variable additional features in NF1 patients." (PMID 34566848, 2021).
breast carcinoma (2 papers, 2022 to 2024). "Next, MDA-MB-231-luc cells were injected into the tail veins of SCID mice to examine the possible role of RNF135 in breast cancer metastasis." (PMID 36495591, 2022). "However, the relationship between RNF135 and breast cancer has not been elucidated." (PMID 36495591, 2022).
learning disabilities (2 papers, 2017 to 2024). "Although other targets of Riplet have not been reported, it was shown that mutations on human Riplet genes (also called RNF135) are linked to learning disabilities and several neuropsychiatric disorders." (PMID 29354136, 2017).
lung carcinoma (2 papers, 2016 to 2023). "To further elucidate the physiological role of RNF135 in regulating the tumorigenesis activity of SCC25 cells in vivo, we established the metastasis lung cancer model through injecting the RNF135 stable knockdown SCC25 cells into the nude mice through tail vein." (PMID 27709798, 2016).
malignant peripheral nerve sheath tumor (2 papers, 2016 to 2024). Malignant peripheral nerve sheath tumor (MPNST) is a rare and often aggressive soft tissue sarcoma occurring in a wide range of anatomical sites. "RNF135 gene has been well studied in malignant peripheral nerve sheath tumors and lymphoblastic leukemia, but our study is the first to link these loci to smoking in non-small cell lung tumors." (PMID 27602958, 2016).
neurofibromatosis (2 papers, 2022 to 2023). A hereditary neoplastic syndrome in which tumors grow in the nervous system. "RNF135 has been associated with ASD and neurofibromatosis and reported to be involved in intronic Alu-mediated recombination in NF1 patients." (PMID 37108679, 2023). "Research has shown that the gene known as RNF135, which was discovered in the course of the genome project, is responsible for neurofibromatosis as well as other hereditary conditions that affect humans." (PMID 36495591, 2022).
triple-negative breast carcinoma (2 papers, 2022 to 2024). An invasive breast carcinoma which is negative for expression of estrogen receptor (ER), progesterone receptor (PR), and human epidermal growth factor receptor 2 (HER2). "In contrast, the correlation between RNF135 expression and triple-negative breast cancer was investigated in this study." (PMID 36495591, 2022).
acute myeloid leukemia (1 paper, 2022). Acute myeloid leukemia (AML) is a group of neoplasms arising from precursor cells committed to the myeloid cell-line differentiation. "CESC (P = 1.3e-03), lung adenocarcinoma (P = 0.02), acute myeloid leukemia (P = 2.7e-03), BRCA (P = 8.6e-17), esophageal carcinoma (P = 4.8e-03), and stomach and esophageal carcinoma (P = 1.2e-07) exhibited significant differences in RNF135 copy number variations (CNV) and mRNA." (PMID 36495591, 2022).
atherosclerosis (1 paper, 2025). A disease characterized by the build-up of fatty material and calcium deposition in the arterial wall resulting in partial or complete occlusion of the arterial lumen. "Since small, nonstenotic carotid plaques represent a unique phenotypic feature of subclinical atherosclerosis, the association between elevated levels of RNF135 and the progression of carotid plaques requires further investigation." (PMID 40727388, 2025). "Recent studies revealed that RNF135 is highly expressed in patients with atherosclerosis and mediates cardiomyocyte survival and repair under ischemic stress, showing its involvement in cardiovascular diseases." (PMID 40727388, 2025).
gastric cancer (1 paper, 2021). A primary or metastatic malignant neoplasm involving the stomach. "The expression of lnc-ABCC5-2:1, lnc-PSCA-4:2 and lnc-RNF135-1:3 in gastric cancer tissues was significantly lower than pericarcinomatous tissue." (PMID 34295803, 2021).
metastatic tumors (1 paper, 2016). "The expression of Ki67 was strongly increased in the metastatic tumors harvested in the RNF135 knockdown group." (PMID 27709798, 2016).
neurofibromatosis type 1 (1 paper, 2014). A clinically heterogeneous, neurocutaneous genetic disorder characterized by cafe-au-lait spots, iris Lisch nodules, axillary and inguinal freckling, and multiple neurofibromas. "Heterozygous 17q11 microdeletions that encompass NF1 and RNF135 cause a subset of neurofibromatosis type 1." (PMID 24963031, 2014).